UBE2NL (ubiquitin conjugating enzyme E2 N like (gene/pseudogene))
Synonyms: Li174
Gene: Protein-coding gene on chromosome X (143,884,071 to 143,885,255, forward strand). Ensembl gene ENSG00000276380.
Subcellular location (Human Protein Atlas): Nucleoplasm; Nucleoli fibrillar center
Homologues: Orthologues: chimpanzee UBE2NL (97% identical), zebrafish ube2na (88% identical), zebrafish ube2nb (88% identical), tropical clawed frog ube2n (82% identical), Caenorhabditis elegans ubc-13 (78% identical), Drosophila melanogaster ben (73% identical), Drosophila melanogaster CG3473 (72% identical). Paralogues in human: UBE2N (91% identical), UBE2K (43% identical), UBE2T (40% identical), UBE2A (37% identical), UBE2B (37% identical), CDC34 (36% identical), UBE2C (36% identical), UBE2R2 (36% identical), UBE2S (35% identical), UBE2J1 (33% identical), UBE2I (32% identical), UBE2G1 (31% identical), and 12 more.
Diseases named in the same sentence as UBE2NL in open-access papers:
UBE2NL is named in the same sentence as 8 diseases in open-access papers, as found by Europe PMC text mining. Sharing a sentence is not in itself a finding about the gene and the disease. The quoted sentences say what the papers report.
endometrial cancer (1 paper, 2025). Primary or metastatic malignant neoplasm involving the endometrium (mucous membrane that lines the endometrial cavity). "In conclusion, this study identifies UBE2NL and HIST2H3PS2 as novel contributors to tumor aggressiveness and metastasis in epithelial ovarian and endometrial cancer." (PMID 40429973, 2025). "We next asked whether the expression of UBE2NL and HIST2H3PS2 also affected clinical outcomes in endometrial cancer (EC) patients." (PMID 40429973, 2025).
gastroschisis (1 paper, 2022). Gastroschisis is marked by viscera protruding, without a covering sac, from the fetal abdomen on the right lateral base of the umbilicus. "UBE2NL has been found to be a novel type 2 diabetes relevant gene and a novel candidate gene in familial gastroschisis." (PMID 35035504, 2022).
gynecologic cancer (1 paper, 2025). "While the oncogenic roles of UBE2N and tumor-derived EVs have been previously reported, our work is the first to demonstrate a functional role for UBE2NL and HIST2H3PS2, particularly in the context of EV-mediated tumor progression in gynecologic cancers." (PMID 40429973, 2025). "Together, the identification of UBE2NL and HIST2H3PS2 in EXs derived from aggressive ovarian cancer cells provides new insights into the molecular underpinnings of gynecologic cancer progression and highlights their potential as prognostic biomarkers and therapeutic targets." (PMID 40429973, 2025). "Targeting UBE2NL, HIST2H3PS2, and their EV-mediated effects may represent a promising new frontier in treating aggressive gynecologic cancers." (PMID 40429973, 2025).
ovarian carcinoma (1 paper, 2025). A malignant neoplasm originating from the surface ovarian epithelium. "Specifically, UBE2NL expression was significantly higher in advanced-stage ovarian cancer tissues compared to early-stage cancer and benign ovarian cysts (mean ± SD: 0.1225 ± 0.2508 vs. 0.0862 ± 0.1662 vs. 0.0037 ± 0.0069; p < 0.001, by Kruskal–Wallis test)." (PMID 40429973, 2025). "This study first identified that high expressions of UBE2NL and HIST2H3PS2 were associated with poor survival outcomes in epithelial ovarian cancer (EOC) patients using TCGA data, and we validated these findings in clinical samples across all subtypes of EOC." (PMID 40429973, 2025). "In this study, we identified two novel EX cargo proteins—UBE2NL and HIST2H3PS2—derived from highly aggressive epithelial ovarian cancer (EOC) cells and mesenchymal-type ovarian stromal progenitor cells (MSC-OCSPCs) but absent in less aggressive SKOV3 cells." (PMID 40429973, 2025).
cancer (1 paper, 2025). A tumor composed of atypical neoplastic, often pleomorphic cells that invade other tissues. "UBE2NL, a ubiquitin-conjugating enzyme-like protein, is structurally related to UBE2N, a protein involved in DNA repair, inflammatory signaling, and cancer progression." (PMID 40429973, 2025).
tumor (1 paper, 2025). "The high expression of UBE2NL and HIST2H3PS2 in MSC-OCSPCs represents their involvement in the tumor microenvironment." (PMID 40429973, 2025). "To assess the functional impact of UBE2NL- and HIST2H3PS2-enriched exosomes (EXs) on tumor cell invasion, we conducted transwell invasion assays using SKOV3 cells with various EX treatments." (PMID 40429973, 2025). "Moreover, the basal expression levels may not fully reflect the functional impact of UBE2NL on tumor aggressiveness." (PMID 40429973, 2025).
UBE2NL also shares sentences with these, for which no sentence is quoted: ovarian tumors (1 paper); type 2 diabetes (1).